ACE (angiotensin I converting enzyme)
Diseases named in the same sentence as ACE in open-access papers (continued):
Sharing a sentence is not in itself a finding about the gene and the disease.
colorectal cancer (continued). "Given that cancer is not the indication for ACE inhibitors, there have not been any RCTs of ACE inhibitor use and colorectal cancer risk specifically." (PMID 41085561, 2026). "We attempted to perform SUSIE, which allows for multiple causal SNPs in the region, but no credible sets were found for colorectal cancer risk in the ACE locus as no SNPs in the colorectal cancer dataset reached the default minimum p-value threshold (1x10-6)." (PMID 41085561, 2026). "ACE inhibition has been shown to downregulate Wnt target genes in colorectal cancer, suggesting that targeting the upstream Wnt/β-catenin pathway alongside the paracrine renin–angiotensin system may be necessary." (PMID 39941158, 2025). "Tumor-associated macrophages of the M2 phenotype are tumorigenic, with ACE regulating their production of inflammatory cytokines; notably, ACE inhibition with the ACE inhibitor captopril increases Kupffer cell infiltration in liver metastasis from colorectal cancer." (PMID 39941158, 2025). "In mendelian randomization analyses examining the association of genetically proxied ACE inhibition with 8 previously reported colorectal cancer risk factors, there was little evidence to support associations." (PMID 35113855, 2022). "In analyses of 23,572 colorectal cancer cases and 48,700 controls of East Asian descent, there was little evidence of association of genetically proxied ACE inhibition and colorectal cancer risk (OR 0.97, 95% CI 0.88 to 1.07; P = 0.59)." (PMID 35113855, 2022). "Our findings for genetically proxied ACE inhibition and colorectal cancer risk are not consistent with some previous conventional observational analyses." (PMID 35113855, 2022). "Prior to confirmation of an effect of ACE inhibitor use on colorectal cancer risk in clinical trials, these findings should not alter clinical practice for ACE inhibitor prescribing." (PMID 35113855, 2022). "Likewise, in analyses using SBP SNPs in ACE, genetically proxied SBP lowering via ACE inhibition was associated with an increased odds of colorectal cancer (OR equivalent to 1 mm Hg lower SBP: 1.11, 95% CI 1.04 to 1.18; P = 1.3 × 10−3)." (PMID 35113855, 2022). "A limitation of this finding is that the magnitude of the effect of ACE inhibition on colorectal cancer may be underestimated, since the effect of ACE inhibitors on lowering ACE levels is likely more potent than the genetic effect from the variants used here as proxies for ACE levels." (PMID 41085561, 2026). "Furthermore, ACE inhibitors and ARBs have been associated with improved survival in metastatic renal cell carcinoma patients and lower colorectal cancer risk following a negative baseline colonoscopy." (PMID 40558670, 2025). "It is therefore possible that adverse effects of ACE inhibition on colorectal cancer risk may likewise not emerge until many years after treatment initiation." (PMID 35113855, 2022). "However, colocalization analysis suggested that colon ACE expression and colorectal cancer risk were unlikely to share a causal variant within the ACE locus (29.1% posterior probability of a shared causal variant)." (PMID 35113855, 2022). "Therefore, it seems that tRAS activation by AT1R in colorectal cancer may occur independently of ACE." (PMID 35346064, 2022). "In addition, extension of the analyses presented in this study to a survival framework could inform on whether concurrent use of ACE inhibitors may have an adverse effect on prognosis among colorectal cancer patients." (PMID 35113855, 2022). "For other cancer sites, for example colorectal cancer (CRC), studies have reported tumor size to be reduced and tumors to be less often metastatic at diagnosis among ACE-inhibitor users." (PMID 34921656, 2022). "Furthermore, it is not clear whether the pharmacological effect of ACE inhibitor drugs in clinical practice extend to the colon, an issue that is critical to resolving their potential effects on colorectal cancer risk." (PMID 35113864, 2022).
colorectal cancer (continued). "Meta-analyses of randomized trials have not reported increased rates of cancer among ACE inhibitor users, though these analyses have not reported findings separately for colorectal cancer." (PMID 35113855, 2022).
diabetic retinopathy (27 papers, 2013 to 2025). "We conducted a comprehensive meta-analysis on 40 published studies with 4252 diabetic retinopathy cases and 5916 controls relating the variant of the ACE I/D to the risk of DR, which can provide better ability to detect smaller effect sizes." (PMID 27854313, 2016). "Detection of the association between a deletion polymorphism in the gene encoding angiotensin I-converting enzyme and advanced diabetic retinopathy." (PMID 23401650, 2013). "However, our study was the first one that investigated the frequency of the ACE gene I/D polymorphism among Jordanian individuals with diabetic retinopathy." (PMID 34177375, 2021). "Although we have identified the critical roles of HMOX1, TLR4, and ACE in diabetic retinopathy through bioinformatics analysis and experimental validation, this study still has several limitations." (PMID 40282274, 2025). "In conclusion, ACE, HMOX1, and ACE have been identified as promising potential diagnostic biomarkers associated with nucleotide metabolism in diabetic retinopathy." (PMID 40282274, 2025). "Further analysis involving PPI network construction and multiple algorithms identified HMOX1, TLR4, and ACE as biomarkers of diabetic retinopathy." (PMID 40282274, 2025). "Genetic variations in genes such as angiotensinogen (AGT), angiotensin-converting enzyme (ACE), and angiotensin II receptor type 1 (AGTR1) have been associated with an increased risk of diabetic retinopathy." (PMID 38918766, 2024). "Our colleagues have previously reported that hypoxia induces ACE production in diabetic retinopathy, leading to AGE production via NADPH." (PMID 37892765, 2023). "Hypoxia induces angiotensin-converting enzyme (ACE) production in diabetic retinopathy, leading to advanced glycation end products (AGEs) production via nicotinamide adenine dinucleotide phosphate (NADPH) in diabetic rats." (PMID 37892765, 2023). "Angiotensin-converting enzyme (ACE) stimulates angiogenesis that leads to the development of diabetic retinopathy (DR)." (PMID 34177375, 2021). "In the present study we determined the association of angiotensin converting enzyme (ACE) and plasminogen activator inhibitor-1 (PAI-1) gene polymorphisms with diabetic retinopathy (DR) and its sub-clinical classes in Pakistani type 2 diabetic patients." (PMID 26658948, 2015). "When diabetic retinopathy occurs, various factors lead to the downregulation of ACE expression." (PMID 40282274, 2025). "Both systemic and local RAAS are implicated in the pathogenesis of retinopathy and all components of the RAAS are expressed in retina with highly elevation of renin, ACE, Ang II and AT1R in patients with diabetic retinopathy." (PMID 26310144, 2015).
dilated cardiomyopathy (27 papers, 2010 to 2025). Cardiomyopathy which is characterized by dilation and contractile dysfunction of the left and right ventricles. "Limited evidence exists for an association between dilated cardiomyopathy (DCM) and the angiotensin-converting enzyme (ACE) gene with an insertion/deletion (I/D) angiotensinogen (AGT) M235T gene polymorphism." (PMID 41209135, 2025). "The patient developed dilated cardiomyopathy at 3 years and 8 months, with progressive left ventricular dysfunction despite early treatment with corticosteroids, ACE inhibitors, and beta-blockers." (PMID 40004149, 2025). "Since dilated cardiomyopathy is a common problem associated with DMD, angiotensin-converting enzyme (ACE) inhibitors are also recommended for those with ventricular dysfunction." (PMID 38283433, 2023). "Pharmacological treatment for cardiac manifestations includes the standard treatments of dilated cardiomyopathy and arrhythmias such as the use of angiotensin converting enzyme (ACE) inhibitors, β-blockers and diuretics." (PMID 36672955, 2023). "The dilated cardiomyopathy was treated with furosemide, captopril and angiotensin converting enzyme (ACE)." (PMID 37144154, 2023). "In an editorial communication in 1995, we commented on the use of ACE inhibitors instead of vasodilators such as hydralazine as afterload reducing agents to treat dilated cardiomyopathy." (PMID 32290258, 2020). "Due to acute sudden death of 2 siblings from 2 unrelated families and rapid cardiac deterioration of 3 other patients, a decision was taken to place all children with DK1-CDG, even with mild dilated cardiomyopathy, on ACE inhibitors, β blockers, and diuretics." (PMID 22327749, 2013). "However, angiotensin-converting enzyme (ACE) inhibitors, angiotensin receptor blockers (ARBs), and β-blockers are the first-line to prevent dilated cardiomyopathy in dystrophinopathy patients." (PMID 37759719, 2023). "While there are no studies proving their value in ARVC patients, there are many trials demonstrating the critical role of ACE inhibitor therapy in patients with ischemic and non-ischemic forms of dilated cardiomyopathy." (PMID 34926342, 2021).
IgA nephropathy (27 papers, 2007 to 2025). "Evidence indicates significant association between the D allele or DD genotype of ACE and the risk for IgA nephropathy in Asian populations." (PMID 28336767, 2017). "Polymorphisms in several genes within the RAAS system, including ACE, angiotensinogen and the angiotensin type 1 receptor, have been linked with cardiovascular and renal disorders, including diabetic nephropathy, IgA nephropathy and uropathies." (PMID 17647026, 2007). "Herein, we also discuss emerging evidence on CHM’s benefits in IgA nephropathy, including reduced proteinuria and inflammation, and its potential synergy with conventional treatments such as angiotensin-converting enzyme (ACE) inhibitors." (PMID 41347220, 2025). "Nevertheless, the influence of anti-CXCR3 antibodies on the course of FSGS and IgA nephropathy cannot be excluded and should be checked using bigger groups of patients who are divided into subgroups according to the dosage of ACE inhibitor received." (PMID 39768675, 2024). "The connection between angiotensin-converting enzyme insertion/deletion (ACE I/D) gene polymorphisms and IgA nephropathy (IgAN) was conflicting." (PMID 34867085, 2021). "In summary, our study showed that aliskiren has anti-proteinuric effect in patients with IgA nephropathy and persistent proteinuria despite ACE inhibitor or ARB therapy." (PMID 23675422, 2013). "In the present study, we found that in patients with IgA nephropathy and persistent proteinuria despite ACE inhibitor or ARB therapy, aliskiren can effectively reduce proteinuria." (PMID 23675422, 2013). "Aliskiren has anti-proteinuric effect in patients with IgA nephropathy and persistent proteinuria despite ACE inhibitor or ARB." (PMID 23675422, 2013). "We studied 22 patients with biopsy-proven IgA nephropathy and persistent proteinuria despite angiotensin converting enzyme (ACE) inhibitor or angiotensin receptor blocker (ARB)." (PMID 23675422, 2013). "Since the beginning of the 1990s, Japanese medical practitioners have extensively prescribed angiotensin-converting enzyme (ACE) inhibitors for children with mild IgA nephropathy (IgA-N) and steriods for those with severe IgA-N." (PMID 18224344, 2008). "The ACE DD genotype, associated with increased RAS activity, was increased in patients with IgA nephropathy who ultimately experienced progressive decline in renal function during follow-up compared with those whose function remained stable over the same time." (PMID 17647026, 2007). "Thus, the Kidney Disease: Improving Global Outcomes (KDIGO) guidelines for glomerulonephritis recommend ACE inhibitors as first-line treatment for patients with IgA nephropathy with proteinuria of more than 1 g/day (recommendation level 1B)." (PMID 36685528, 2022). "In the lower HRR group of IgA nephropathy patients ACE-inhibitors and ARBs were administered in higher proportions, thus RAAS blocker therapy alone could not have prevented the occurrence of primary and secondary endpoints." (PMID 34809611, 2021).
syphilis (27 papers, 2012 to 2026). A contagious bacterial infection caused by the spirochete Treponema pallidum. "Laboratory investigation such as Full blood count, ESR, HIV test, RPR for Syphilis, and serum angiotensin converting enzyme (ACE) were done which were normal." (PMID 27279946, 2016). "His angiotensin-converting enzyme (ACE) level was normal, and serological testing for syphilis, Lyme disease, cytomegalovirus (CMV), and toxoplasma was negative." (PMID 27247899, 2016). "Level of angiotensin-converting enzyme (ACE) was normal; the results of serological testing for syphilis, Lyme disease, herpes simplex virus, varicella zoster virus, cytomegalovirus, and toxoplasma was negative; and brain magnetic resonance imaging was normal." (PMID 27247899, 2016). "The following tests can rule out the main differential diagnosis: syphilis serology, ACE level, Interferon gamma release assay, and chest X-ray." (PMID 36013011, 2022).
nephrotic syndrome (26 papers, 2009 to 2025). A collection of symptoms that include severe edema, proteinuria, and hypoalbuminemia; it is indicative of renal dysfunction. "Angiotensin converting enzyme (ACE) (I/D) gene association studies are important for detecting kidney disease and herein we assessed the association of ACE (I/D) polymorphism with nephrotic syndrome in South Indian children." (PMID 30333281, 2019). "The results from the published studies on the association betweenangiotensin-converting enzyme (ACE) insertion/deletion (I/D) genepolymorphism and the treatment response to steroid in Asian children withidiopathic nephrotic syndrome (INS) is still conflicting." (PMID 21611163, 2011). "Depending on the complications of nephrotic syndrome, patients with this disease receive supportive treatment with diuretics, ACE inhibitors or angiotensin-receptor blockers, lipid-lowering agents and anticoagulants." (PMID 38004046, 2023). "We conducted a successful medical nephrectomy using ACE inhibitor in 6 out of 8 patients with nephrotic syndrome." (PMID 35463874, 2022). "Patients with refractory nephrotic syndrome despite concurrent ACE inhibitor therapy were consented and randomized to two different doses of ACTH for six months." (PMID 24159603, 2013). "As expected, nephrotic syndrome was steroid-resistant with limited response to ACE inhibitor." (PMID 35956038, 2022). "The management of these patients is associated with a symptomatic treatment such as sodium and water restriction, diuretics and ACE inhibitors and a prophylaxis of specific complications of nephrotic syndrome including thromboembolism, infections and lipid abnormalities." (PMID 19830148, 2009). "There was a response to deltacortil within 2 weeks but she again developed edema while tapering the deltacortil so labeled as steroid-dependent nephrotic syndrome and was given cyclosporin along with ACE (Angiotensin-converting enzyme) inhibitors." (PMID 36556986, 2022). "This prompted us to evaluate the antiproteinuric effect of spironolactone in patients with nephrotic syndrome secondary to idiopathic membranous nephropathy (IMN) and persistent proteinuria despite full dose ACE inhibitor therapy." (PMID 27713239, 2010). "This genetic form of nephrotic syndrome usually does not respond to steroid treatment; nevertheless, transient reductions in proteinuria using ACE-inhibitors, NSAID or even cyclosporine-A have been documented." (PMID 24589093, 2014).
prostate carcinoma (26 papers, 2011 to 2025). A carcinoma that arises from epithelial cells of the prostate gland. "Another study found that individuals with the ACE genotype tend to smoke and that smoking increases renin activity, which promotes angiotensin II production, increasing the risk of prostate cancer." (PMID 38487860, 2024). "This meta-analysis aims to explore the association between angiotensin-converting enzyme (ACE) insertion/deletion (I/D) gene polymorphism and susceptibility to prostate cancer (PCa)." (PMID 36329458, 2022). "ACE mutations have been reported to be involved in a number of lymph node metastases of gastric cancer and associated with a worse prognosis in prostate cancer." (PMID 34458283, 2021). "The use of ACE inhibitors was associated with better outcomes in patients with different tumors (including prostate cancer) who were receiving chemotherapy or anti-VEGF therapy [reviewed in 15]." (PMID 31695843, 2019). "There were ten studies that reported the relationship between the use of ACE inhibitors and the risk of prostate cancer." (PMID 29514670, 2018). "Some case-control studies showed significantly increased risk between ACE inhibitor usage and prostate cancer, while a previous meta-analysis showed that ACE inhibitors or angiotensin-receptor blockers did not affect the occurrence of cancer." (PMID 29514670, 2018). "Therefore, the differences between ACE I/D polymorphism and prostate cancer susceptibility are inconclusive among the populations in different regions, which need to be verified by more studies in the future." (PMID 36329458, 2022). "Some studies, as well as our previous study, support the hypothesis that ACE genetic variants may affect the production of angiotensin II (Ang II) and the progression of human prostate cancer." (PMID 26760503, 2016). "Other conditions that are exacerbated by high ACE activity, such as prostate cancer, are potentially affected by SARS-CoV-2 infection, which reduces ACE2 since reduced ACE2 implies upregulated ACE activity." (PMID 32974166, 2020). "Here, we report the ACE phenotyping on prostate cancer tissues in comparison with normal prostate tissues and prostate tissues from patients with BPH." (PMID 31695843, 2019). "The topic of the relationship between the use of antihypertensive drugs and the risk of prostate cancer remain controversial, especially in the use of CCB and ACE inhibitors or ARB." (PMID 29514670, 2018). "Moreover, the conformational fingerprint of prostate ACE was shown to be quite different from that for lung ACE that opens up a theoretical possibility for the use the appearance of prostate-specific ACE in the blood as an early marker of prostate cancer." (PMID 31695843, 2019). "Our largely null findings for genetically proxied ACE inhibition and risk of breast, lung, and prostate cancer risk are not consistent with some previous observational reports that compared ACE inhibitor users to nonusers or to users of β blockers or thiazide diuretics." (PMID 35113855, 2022). "If angiotensinogen is produced at higher levels in adjacent cells one ofthe activating enzymes which convert the product of the AGTgene in angiotensin II (ACE) is instead higher in PIN andL-PCA, suggesting the potential for utilization in tumour cells at lower stagesof prostate cancer development." (PMID 21479216, 2011).